CORO7-PAM16 (CORO7-PAM16 readthrough)
Gene: Protein-coding gene on chromosome 16 (4,340,251 to 4,420,494, reverse strand). Ensembl gene ENSG00000103426.
Genetic constraint (gnomAD): Loss-of-function variants: 117 observed, 131.03 expected, observed/expected ratio (o/e) 0.89, 90% interval 0.77 to 1.04. The upper end of that interval is the gene's LOEUF score, 1.04, which puts it in group 4 of 6, group 1 being the genes least tolerant of losing a copy. Missense variants: 1,510 observed, 1,354.3 expected, observed/expected ratio (o/e) 1.12, 90% interval 1.07 to 1.16. Synonymous variants: 675 observed, 582.07 expected, observed/expected ratio (o/e) 1.16, 90% interval 1.09 to 1.24.